TNFAIP2 (TNF alpha induced protein 2)
Description:
May play a role as a mediator of inflammation and angiogenesis.
Synonyms: B94; EXOC3L3
Tractability: PROTAC: ubiquitination databases record sites on it; its protein half-life has been measured.
Gene: Protein-coding gene on chromosome 14 (103,121,407 to 103,137,441, forward strand). Ensembl gene ENSG00000185215.
Subcellular location (Human Protein Atlas): Cytosol; Golgi apparatus; Nuclear membrane; Nucleoplasm
Gene Ontology:
Molecular function: protein binding; SNARE binding
Biological process: exocyst localization; exocytosis
Cellular component: extracellular region; exocyst
Genetic constraint (gnomAD): Loss-of-function variants: 41 observed, 47.76 expected, observed/expected ratio (o/e) 0.86, 90% interval 0.67 to 1.11. The upper end of that interval is the gene's LOEUF score, 1.11, which puts it in group 4 of 6, group 1 being the genes least tolerant of losing a copy. Missense variants: 600 observed, 614.86 expected, observed/expected ratio (o/e) 0.98, 90% interval 0.91 to 1.04. Synonymous variants: 299 observed, 272.84 expected, observed/expected ratio (o/e) 1.1, 90% interval 1 to 1.21.
Homologues: Orthologues: chimpanzee TNFAIP2 (99% identical), macaque TNFAIP2 (84% identical), dog TNFAIP2 (79% identical), pig TNFAIP2 (77% identical), rat Tnfaip2 (73% identical), guinea pig TNFAIP2 (73% identical), mouse Tnfaip2 (72% identical), rabbit TNFAIP2 (65% identical), tropical clawed frog tnfaip2 (32% identical), zebrafish tnfaip2b (25% identical), zebrafish tnfaip2a (23% identical). Paralogues in human: EXOC3L2 (24% identical), EXOC3L4 (23% identical), EXOC3L1 (22% identical), EXOC3 (21% identical).
Diseases named in the same sentence as TNFAIP2 in open-access papers:
TNFAIP2 is named in the same sentence as 76 diseases in open-access papers, as found by Europe PMC text mining. Sharing a sentence is not in itself a finding about the gene and the disease. The quoted sentences say what the papers report.
breast carcinoma (10 papers, 2018 to 2025). "In this study, we found that TNFAIP2 is essential for HIF1α transcriptional expression, thereby facilitating breast cancer angiogenesis." (PMID 39532855, 2024). "In conclusion, our research elucidated the role of TNFAIP2 in promoting angiogenesis in breast cancer." (PMID 39532855, 2024). "(A–F) TNFAIP2 knockdown increased the sensitivity ofHCC1806 breast cancer cells to EPI and BMN in vivo." (PMID 37787041, 2023). "KLF5 promotes migration and invasion by upregulating the transcription of TNFAIP2, a tumor necrosis factor-α (TNFα)-induced gene in breast cancer cells." (PMID 33424607, 2020). "The expression of TNFAIP2 was found to be abnormal in various cancers, including breast cancer, esophageal squamous cell carcinoma, and glioma." (PMID 33109108, 2020). "In that regard, previous studies showed that KLF5 promotes breast cancer cell migration and invasion by upregulating transcription of TNFAIP2, and that KLF5 controls keratinocyte migration via the integrin-linked kinase." (PMID 31327760, 2019). "Furthermore, knockdown of TNFAIP2 attenuated the proangiogenic effects induced by hypoxia in both breast cancer cell lines." (PMID 39532855, 2024). "TNFAIP2 promotes breast cancer angiogenesis via the Rac1-ERK-AP1-HIF1α axis." (PMID 39532855, 2024). "We observed that depletion of TNFAIP2 suppressed breast cancer cell growth in vivo." (PMID 37787041, 2023). "In summary, ITGB4 and TNFAIP2 play important roles in breast cancer chemoresistance." (PMID 37787041, 2023). "TNFAIP2 regulates the actin cytoskeleton, especially the membrane protrusions, to promote cell migration and invasion by regulating the activity of the small GTPase Cdc42 and Rac1 in breast cancer and nasopharyngeal carcinoma." (PMID 30145807, 2018). "Since TNFAIP2 plays an important role in cell migration and invasion in breast cancer, nasopharyngeal carcinoma and oesophageal squamous cell carcinoma, it would be significant to further determine whether TNFAIP2 promotes metastasis in a mouse xenograft tumour model." (PMID 30145807, 2018). "Building upon these findings, our research has demonstrated that TNFAIP2 can induce the transcription of HIF1α via the Rac1-ERK-AP1 signaling pathway, thereby promoting tumor angiogenesis in breast cancer." (PMID 39532855, 2024). "We previously found that TNFAIP2 was regulated by KLF5 and interacted with the small GTPases RAC1 and CDC42, thereby regulating the actin cytoskeleton and cell morphology in breast cancer cells." (PMID 37787041, 2023). "In breast cancer, for example, KLF5 promotes cell proliferation, migration and invasion by up-regulating expression of TNFAIP2." (PMID 31327760, 2019). "Additionally, KLF5 expression is reduced in prostate cancer, leading to the inhibition of angiogenesis, whereas in breast cancer, KLF5 promotes angiogenesis by binding to the promoters of tumor necrosis factor (TNF)α-induced protein 2 (TNFAIP2)." (PMID 40038579, 2025). "Besides, KLF5 promotes breast cancer angiogenesis in part through TNF-α-induced protein 2 (TNFAIP2), an angiogenetic factor increasing capillary tube formation, and KLF5 positively regulates TNFAIP2 by directly binding to its promoter." (PMID 33493334, 2021).
nasopharyngeal carcinoma (10 papers, 2014 to 2025). A carcinoma arising from the nasopharyngeal epithelium. "The elevated TNFAIP2 expression was significantly associated with shorter distant metastasis-free survival among patients with nasopharyngeal carcinoma." (PMID 25383966, 2014). "Furthermore, TNFAIP2 expression is associated with the intratumoral microvessel density in nasopharyngeal carcinomas." (PMID 39532855, 2024). "Apart from its physiologically high expression in macrophages, TNFAIP2 is aberrantly expressed in nasopharyngeal carcinoma cells." (PMID 39939179, 2025). "TNFAIP2 is highly expressed in various malignant tumours, such as nasopharyngeal carcinoma, triple-negative breast cancer, and glioma." (PMID 38271140, 2024). "Knockdown of TNFAIP2 in nasopharyngeal carcinoma HK1 cells dramatically reduced cell migration and invasion but had no significant impact on cell growth." (PMID 30145807, 2018). "In the TNFAIP2 high expression nasopharyngeal carcinoma specimen group, 40.5% of patients developed distant metastasis; this proportion was only 12.1% in the TNFAIP2 low expression group." (PMID 30145807, 2018). "Higher expressed TNFAIP2 in nasopharyngeal carcinoma tumor specimens was found compared to adjacent normal tissues." (PMID 25383966, 2014). "As a novel oncoprotein, tumor necrosis factor alpha-induced protein 2 (TNFAIP2) was reported to be induced by retinoic acid, human papillomavirus and Epstein‒Barr virus in acute promyelocytic leukemia, cervical cancer and nasopharyngeal carcinoma, respectively." (PMID 37525222, 2023). "The abnormal expression of TNFAIP2 has been identified in various malignant tumors, involved in unlimited proliferation, angiogenesis, and migration, including urothelial cancer, esophageal squamous cell carcinoma, and nasopharyngeal carcinoma." (PMID 34136377, 2021). "For example, TNFAIP2 was an independent prognostic factor for nasopharyngeal carcinoma and TNFAIP2 3′ UTR rs8126 may shorten the survival time of patients with septic shock." (PMID 32793480, 2020). "The expression of TNFAIP2 is significantly correlated with low distant metastasis‐free survival in patients with nasopharyngeal carcinoma, and high levels of TNFAIP2 expression indicate shorter disease‐free survival in oesophageal squamous cell carcinoma patients." (PMID 30145807, 2018). "In nasopharyngeal carcinoma, the latent membrane protein 1 (LMP1) can transcriptionally induce TNFAIP2 expression via NF‐κB." (PMID 30145807, 2018).
glioma (9 papers, 2015 to 2025). A benign or malignant brain and spinal cord tumor that arises from glial cells (astrocytes, oligodendrocytes, ependymal cells). "TNFAIP2 is a primary response gene of TNFα, and high expression is associated with increased cell proliferation, migration, invasion and metastasis in various cancers including breast and esophagus cancers and gliomas." (PMID 37511403, 2023). "Glioma studies show predominantly tumour-suppressive activity via TNFAIP2 and caspase pathways, yet upregulation can enhance proliferation and migration through FIH-1/HIF-1α signalling." (PMID 41379397, 2025). "The analyses of the overall survival of patients with gliomas harboring a low or high expression of the TNF Alpha Induced Protein 2 (TNFAIP2) transcript indicates that high expression levels of TNFAIP2 were associated with poor prognosis (p = 1.2 × 10−4)." (PMID 33096700, 2020). "The present study demonstrated that miR-184 was markedly down-regulated in human glioma cells and tissues, TNFAIP2 was up-regulated in human glioma cells and tissues, and TNFAIP2 expression was inversely correlated with miR-184 expression." (PMID 25888093, 2015). "Studies have shown that miR-184 was down-regulated in glioma and TNFα-induced protein 2 (TNFAIP2) was closely related to tumorigenesis." (PMID 25888093, 2015). "The results confirmed that both TNFAIP2 mRNA and protein expressions were substantially down-regulated by the high expression of miR-184 in gliomas." (PMID 25888093, 2015). "Western blotting results further confirmed that the expression level of TNFAIP2 protein was higher in 5 glioma cell-lines than in normal human astrocyte 1800 cells." (PMID 25888093, 2015). "The immunohistochemical staining results also showed that the glioma xenografts of the U87-miR-184 group expressed less TNFAIP2 than the tumors in the U87-negative group." (PMID 25888093, 2015). "As in other reports, the results of the present study indicated that miR-184 could regulate TNFAIP2 in glioma cells." (PMID 25888093, 2015). "Therefore, both TNFAIP2 mRNA and protein expressions were down-regulated by ectopic miR-184 in glioma cells." (PMID 25888093, 2015). "The results of this experiment implied that miR-184 might be a suppressor gene and conformed that miR-184 could target TNFAIP2 in gliomas." (PMID 25888093, 2015). "These collective results suggested that TNFAIP2 is a genuine target of miR-184 in gliomas." (PMID 25888093, 2015). "In human gliomas, TNFAIP2 was one of the specific targets of miR-184." (PMID 25888093, 2015). "The function and mechanism of TNFAIP2 in gliomas need further investigation." (PMID 25888093, 2015). "QRT-PCR results showed that the mRNA expression level of TNFAIP2 was up-regulated in 5 glioma cell-lines compared to 5 normal brain samples, and highly expressed in 81 glioma tissues (WHO grade I, 2 cases; II, 27 cases; III, 24 cases; and IV, 28 cases) compared to non-neoplastic brain tissues." (PMID 25888093, 2015). "Biological information software have predicted that miR-184 could target TNFα-induced protein 2 (TNFAIP2), Which was further validated by Western blot and qRT-PCR in glioma cells." (PMID 25888093, 2015). "The results showed that miR-184 may regulate the expression of TNFAIP2 by binding to the 3′-UTR of TNFAIP2 mRNA and affecting its translation in gliomas." (PMID 25888093, 2015). "Protein and mRNA expression of TNFAIP2 were inversely correlated with miR-184 in glioma." (PMID 25888093, 2015). "miR-184 could regulate TNFAIP2 expression and affected its translation in glioma." (PMID 25888093, 2015). "Therefore, the expressions of miR-184 and TNFAIP2 were negatively correlated in gliomas." (PMID 25888093, 2015). "The type 1 tunneling membrane nanotube-related transcripts (TNFAIP2, S100A4, ERp29) were significantly overexpressed in gliomas compared to normal brain." (PMID 33096700, 2020). "However, the biological function and molecular mechanism of TNFAIP2 in gliomas remain unclear." (PMID 25888093, 2015).
glioma (continued). "The present study is first to report that both mRNA and protein expression levels of TNFAIP2 are up-regulated in glioma cell-lines and tissues compared to non-neoplastic brain tissues." (PMID 25888093, 2015). "The expression and function of TNFAIP2 have not been studied in gliomas; the relationship between TNFAIP2 and miR-184 also has not been studied." (PMID 25888093, 2015). "The study’s results showed that the expression level of TNFAIP2 was higher in human gliomas than in noncancerous brain tissues." (PMID 25888093, 2015). "TNFAIP2 expression and its correlation with miR-184 in gliomas have not been previously reported." (PMID 25888093, 2015). "The expression of TNFAIP2 was higher in 81 glioma samples compared to noncancerous brain tissues." (PMID 25888093, 2015).
acute myeloid leukemia (6 papers, 2012 to 2024). Acute myeloid leukemia (AML) is a group of neoplasms arising from precursor cells committed to the myeloid cell-line differentiation. "Nonetheless, to date only one study has demonstrated the functional impact of a somatic mutation that creates a miRNA target site within TNFAIP2, in acute myeloid leukemia." (PMID 28704519, 2017). "A somatic mutation of the TNFAIP2 gene in an acute myeloid leukemia (AML) patient results in a Dicer‐dependent repression, suggesting the creation of a new miR‐BS for a yet unidentified miRNA." (PMID 26992833, 2016). "Recently, a somatic mutation in the 3′UTR of TNFAIP2, a known target of the PRAM1 oncogene, creates a new miRNA target site that results in a reduction of TNFAIP2 expression in a patient with acute myeloid leukemia." (PMID 23091610, 2012). "However, the potential role of TNFAIP2 in the development of acute myeloid leukemia (AML) remains unknow yet." (PMID 36243694, 2022). "TNFAIP2 (tumor necrosis factor, alpha-induced protein 2) was also found to be hypermethylated in colorectal cancer and NPM2 (nucleophosmin/nucleoplasmin 2) in melanoma and acute myeloid leukemia." (PMID 26646589, 2016).
gastric cancer (6 papers, 2013 to 2025). A primary or metastatic malignant neoplasm involving the stomach. "TNFAIP2 SNPs are associated with prognosis and risk stratification in a variety of tumors, including squamous cell carcinoma and gastric cancer, strongly suggesting their potential role in AML." (PMID 40230861, 2025). "This study aims to understand the correlation between TNFAIP2 gene polymorphism and prediction as well as prognosis of gastric cancer (GC) in a Chinese population." (PMID 32793480, 2020). "In this study, we investigated associations between potentially functional SNPs in the miRNA binding sites of the 3′UTR of TNFAIP2 and gastric cancer risk in a US population." (PMID 23724109, 2013). "In this hospital-based case-control study, we found that the TNFAIP2 miR-184 binding site variant rs8126 CC genotype was significantly associated with an elevated risk of developing gastric cancer in a recessive genetic model." (PMID 23724109, 2013). "Logistic regression analysis of associations between the genotypes of TNFAIP2 and gastric cancer risk." (PMID 23724109, 2013). "However, our study discovered that TNFAIP2 expression was positively linked with prognosis, implying that it performs an opposing effect in individuals with gastric cancer." (PMID 36479092, 2022). "Stratification analysis for associations between the TNFAIP2 rs8126 SNP and gastric cancer risk." (PMID 23724109, 2013). "Our data suggested that the TNFAIP2 miRNA binding site rs8126 T>C SNP may be a marker for susceptibility to gastric cancer, and this finding requires further validation by larger studies." (PMID 23724109, 2013). "Although our study did not reveal any main effect of other SNPs in the miRNA binding sites of TNFAIP2 on overall risk of gastric cancer, we did find that the rs8126 CC variant homozygous genotype, compared with the combined genotypes (TC+TT), was associated with significantly increased cancer risk." (PMID 23724109, 2013). "Haplotype analysis for genotypes of TNFAIP2 and Gastric Cancer risk." (PMID 23724109, 2013). "The interaction effects between TNFAIP2 TagSNPs and environmental factors on gastric cancer (GC) risk." (PMID 32793480, 2020). "The correlation between TNFAIP2 rs8126 polymorphism and gastric cancer (GC) prognosis in the subgroup analysis." (PMID 32793480, 2020). "The correlation between TNFAIP2 TagSNPs and gastric cancer (GC) risk in the general population." (PMID 32793480, 2020). "The correlation between TNFAIP2 TagSNPs and gastric cancer (GC) risk in the subgroup population." (PMID 32793480, 2020). "In gastric cancer and SCCHN, miR-184 bonded to the 3′-UTR of TNFAIP2, and the miR-184 binding site single nucleotide polymorphisms in TNFAIP2 contributed to tumor susceptibility." (PMID 25888093, 2015). "However, since the present study is, to our knowledge, the first study on the TNFAIP2 SNPs and gastric cancer risk, our findings are best considered preliminary, and larger studies are warranted to further assess the role of these SNPs in the etiology of gastric cancer." (PMID 23724109, 2013). "Therefore, we hypothesized that TNFAIP2 SNPs are associated with susceptibility to gastric cancer." (PMID 23724109, 2013). "In the present study with a limited sample size, the selected SNP rs8126 T>C SNP in the TNFAIP2 miRNA binding site, a SNP that was not included, nor in LD with those included, in the GWAS chip, was associated with gastric cancer." (PMID 23724109, 2013). "The correlation between serum TNFAIP2 protein expression and clinicopathological parameters in gastric cancer (GC) patients." (PMID 32793480, 2020). "To test this hypothesis, we conducted a case-control study to evaluate the association between these four TNFAIP2 SNPs in miRNA binding sites and risk of gastric cancer in a US non-Hispanic white population." (PMID 23724109, 2013). "Serum TNFAIP2 protein expression between gastric cancer (GC) patients and healthy persons." (PMID 32793480, 2020).
gastric cancer (continued). "The correlation between TNFAIP2 SNPs and gastric cancer (GC) prognosis in the general analysis." (PMID 32793480, 2020). "The correlation between serum TNFAIP2 protein expression and gastric cancer (GC) prognosis." (PMID 32793480, 2020). "However, none of other TNFAIP2 SNPs was associated with risk of gastric cancer." (PMID 23724109, 2013).
head and neck squamous cell carcinoma (5 papers, 2015 to 2025). A squamous cell carcinoma that arises from any of the following anatomic sites: lip and oral cavity, nasal cavity, paranasal sinuses, pharynx, larynx, and salivary glands. "The miR-184 binding site single nucleotide polymorphisms [SNP (rs8126 T > C)] in the 3′-UTR of TNFAIP2 modulated TNFAIP2 expression and contributed to susceptibility to squamous cell carcinoma of the head and neck (SCCHN)." (PMID 25888093, 2015). "Recently, some studies have confirmed the relationship between TNFAIP2 SNPs and malignant tumors such as head and neck squamous cell carcinoma (SCCHN) and esophageal squamous cell carcinoma (ESCC), which is beneficial for screening high-risk groups and predicting outcomes of tumors." (PMID 32793480, 2020). "Teng Xu and colleagues identified that, in head and neck squamous cell carcinoma (HNSCC), the DLG motif within tumor necrosis factor-α-induced protein 2 (TNFAIP2) competes with the Kelch domain of Keap1, thereby inhibiting the ubiquitin-proteasome-mediated degradation of NRF2." (PMID 40258841, 2025).